TLR4 (toll like receptor 4)
Diseases named in the same sentence as TLR4 in open-access papers (continued):
Sharing a sentence is not in itself a finding about the gene and the disease.
prostate carcinoma (continued). "In conclusion, these results demonstrate that MPSSS can not only effectively inhibit the growth of prostate cancer as we previously reported but also alter the function of prostate CAFs by activating the TLR4-NF-κB pathway, providing a new strategy for the comprehensive treatment of tumors." (PMID 30992392, 2019). "Knockout of TLR4 in PC3 prostate cancer cells decreases tumor cell migration and invasion." (PMID 29928275, 2018). "However, increased TLR4 expression and increased TLR4 responsiveness have been observed in prostate cancer cells." (PMID 29928275, 2018). "The expression of TLR4 in prostate cancer has been demonstrated in several animal models." (PMID 25101092, 2014). "Peroxiredoxin 1 (Prx1) appears to be an agonist of TLR4 in prostate cancer development." (PMID 25101092, 2014). "Furthermore, TLR4 stimulation by LPS is shown to contribute to chemoresistance to docetaxel in prostate cancer cells." (PMID 25101092, 2014). "When silencing TLR4 expression, the invasion, survival, and tumorigenicity of human prostate cancer cells was inhibited, which indicates TLR4 plays a significant role in connecting inflammation and cancer invasion and progression; however, the exact mechanism is still not clear." (PMID 22938142, 2012). "On the other hand, a comprehensive Swedish study on 20 TLR signaling pathway genes found significant association between two polymorphisms with prostate cancer mortality that did not include TLR4-rs4986790." (PMID 21931695, 2011). "Moreover, downregulation of TLR4 expression by siRNA can inhibit prostate cancer cell invasion in vitro and can improve survival of tumor-bearing animals." (PMID 22110526, 2011). "Furthermore, TLR4 has been detected in clinical prostate cancer specimens." (PMID 41601666, 2026). "Intestinal IRI-induced pIκBα protein levels in the hippocampus were significantly reduced by 4-MU, suggesting that hyaluronan may positively modulate the multi-subunit IκB kinase (IKK), as previously observed in prostate cancer cells, possibly via hyaluronan receptors alternative to TLR4." (PMID 41155357, 2025). "Therefore, it is possible that treatment of ERG-positive prostate cancer with TLR4 inhibitors could simultaneously inhibit ERG function and decrease resistance to chemotherapy." (PMID 33554122, 2021). "However, multiple lines of evidence shows that TLR4 expression is increased in prostate tissues from prostate cancer patients, and altered TLR4 signals may promote cancer development, as well as antitumor effects." (PMID 29928275, 2018). "Thus, TLR4-related innate immune activation and inflammation may play a role in the etiology and progression of prostate cancer." (PMID 29928275, 2018). "In addition, we hypothesize that long-term stimulation through TLR4 signaling in prostate cancer may lead to altered TLR4 responsiveness in tumor microenvironment." (PMID 29928275, 2018). "A TLR4 gene single nucleotide polymorphism may be associated with the risk of prostate cancer though results are not consistent." (PMID 29928275, 2018). "Furthermore, TLR4 stimulation may have indirect effects on promoting prostate cancer development through reducing immune function in the tumor microenvironment." (PMID 29928275, 2018). "TLR4 overexpression has been detected in various tumor cell lines and could predict the tumor growth or recurrence in gastric tumors, oral tongue squamous cell carcinoma and prostate cancer recurrence." (PMID 28484456, 2017). "In addition, TLR4 has also been shown to be expressed in clinical samples of prostate cancer." (PMID 25101092, 2014). "All together this shows that NOB treatment alone has a greater anti-inflammatory effect on the inhibition of both the TLR4/TRIF/IRF3 and TLR9/IRF7 signaling pathways in prostate cancer than when combined with LPS or CpG-ODN treatment." (PMID 41601666, 2026).
prostate carcinoma (continued). "In prostate cancer, activation of TLR2, TLR4, and TLR9 stimulates tumor growth while activation of TLR3, TLR4, TLR5, and TLR7 suppress tumor development." (PMID 41601666, 2026). "TLR4 and COX-2 expression are elevated in prostate cancer, and silencing their expression through p65 phosphorylation inhibition leads to tumor growth and invasion." (PMID 41601666, 2026). "A previous study using PC3, a human prostate cancer cell line, found that selenium inhibits the expression of TGF-β1 by TLR4-NF-κB signaling blockade." (PMID 39813754, 2024). "TLR4 activation increases the expression of VEGF and TGF-β1 in prostate cancer cells, which promotes tumor development." (PMID 36030212, 2022). "CRD domain of SP-D is known to interact with CD14, TLR-2, TLR-4, EGFR, and SIRPα that are reported to be present on prostate cancer cells and normal prostate tissues." (PMID 31355132, 2019). "A S100A9-binding small molecule (ABR-215050) that inhibits the interaction between S100A9 and TLR4, the major receptor required for chemically-induced oral carcinogenesis, is presently in Phase III clinical trial for treating prostate cancer." (PMID 26315114, 2015). "It was shown that highly metastatic human prostate cancer cell lines, such as PC3 or DU145, express higher levels of TLR4 compared to poorly metastatic cell lines." (PMID 22110526, 2011). "The triggering of TLR4 and TLR9 on prostate cancer cells has also been shown to promote tumour cell proliferation through increased NF-κB activation." (PMID 20145615, 2010). "Recent reports have revealed that lipids could promote CRC progression by upregulating β2-adrenergic receptor and toll-like receptor 4 (TLR4) expression and could activate the STAT3 signaling pathway in prostate cancer as a signal transduction mediator." (PMID 38263401, 2024). "While TLR4 has been postulated as a potential therapeutic target for prostate cancer, it has not previously been targeted pharmacologically." (PMID 33554122, 2021). "Positively-identified TLR2 protein in all prostate cancer cells and TLR4 protein in PC3 and LNCaP by Western blotting was not accompanied by cell surface expression, as judged by flow cytometry." (PMID 24966802, 2014). "We have shown here that the absence of S100A9 or TLR4 expression delays tumor incidence in a spontaneous prostate cancer model." (PMID 22470535, 2012). "Moreover, the absence of S100A9 or TLR4 expression delays tumor incidence in a spontaneous prostate cancer model." (PMID 26315114, 2015). "Our results showed that surface expression of TLR2 and TLR4 in prostate cancer cells is not affected by such treatments suggesting that TLR2 and TLR4 expressions are differentially regulated in a cell-specific fashion." (PMID 24966802, 2014).
pneumonia (79 papers, 2006 to 2026). An acute, acute and chronic, or chronic inflammation focally or diffusely affecting the lung parenchyma, caused by an infection in one or both of the lungs (by bacteria, viruses, fungi, or mycoplasma.). "The role of TLR4 during A. baumannii infection has been examined in murine septicemia, acute pneumonia, UTI, and catheter-associated UTI (CAUTI) models." (PMID 40817088, 2025). "Toll-like receptors (TLRs) are an important class of proteins involved in natural immunity and are also key receptors for the production of inflammatory mediators, among which TLR4 is closely related to pneumonia caused by IAV." (PMID 35669119, 2022). "Further investigation of the effect of TLR1 and TLR4 polymorphisms in the immunological response in pneumonia is needed." (PMID 34603755, 2021). "As shown in our previous studies, capsular polysaccharides from pathogenic Klebsiella pneumonia activate macrophages through TLR4." (PMID 34944043, 2021). "A comparative analysis of the genotype/allele frequencies for the rs5743551 (TLR1), rs5743708 (TLR2), and rs4986790 (TLR4) polymorphisms was carried out depending on the outcome of pneumonia (recovery/death)." (PMID 34603755, 2021). "Supporting this, inhibition or genetic manipulation of TLR4 reduces the proliferation capacity of Influenza-A Virus and the pro-inflammatory response linked to pneumonia and acute lung injury." (PMID 32973815, 2020). "Pneumonia was induced in wild type (Wt), TLR4 deficient (tlr4−/−) and RAGE deficient (rage−/−) mice by intranasal inoculation of 1 × 107 colony-forming units (CFU) of a USA300 S." (PMID 24342460, 2013). "Using TLR2/4 double-deficient mice we show that TLR2 and TLR4 regulate IFNγ-secretion in vivo during pneumonia caused by C. pneumoniae." (PMID 22096480, 2011). "LPS is an important factor in triggering pneumonia and has been widely studied for its potential to cause endothelial barrier dysfunction; it can effectively activate immune cells via TLR-4 and induce a variety of pro-inflammatory mediators and cytokines through different signaling pathways." (PMID 38339153, 2024). "Additionally, we clearly demonstrated that carriers of either TLR2-rs5743708 or TLR4-rs4986791 polymorphisms, as a whole group, displayed a significant risk for pneumonia development and more severe disease." (PMID 37766191, 2023). "Finally, carriers of either TLR2-rs5743708 or TLR4-rs4986791 polymorphism also displayed a significantly increased risk for developing pneumonia and more severe disease." (PMID 37766191, 2023). "Moreover, individuals carrying either the TLR2-rs5743708 or the TLR4-rs4986791 polymorphisms exhibited a 3.6- and 2.5-fold increased probability for developing pneumonia and a more severe disease, respectively." (PMID 37766191, 2023). "Both MyD88‐ and TRIF‐dependent pathways are implicated in TLR4‐mediated lung injury in pneumonia." (PMID 31350813, 2019). "Toll‐like receptor 4‐deficient mice are valuable to study the role of TLR4 in pneumonia in vivo." (PMID 31350813, 2019). "LPS, as a gram-negative bacterial constituent, is a well-known and established cause of adventitious pneumonia from the community or hospital patients, and Toll-like receptor-4 (TLR4) activation by this stimuli is a reasonable way for activating the innate immunity against gram-negative pathogen/s." (PMID 30609661, 2019). "In addition, we observed that carriers of TLR2-rs5743708 and TLR4-rs4986791 SNPs displayed a 3.7- and 2.2-fold increased risk for developing pneumonia, respectively, also affecting the risk for a more severe disease; however, the statistical differences were not marginally significant." (PMID 37766191, 2023). "Baicalin was identified to alleviate acute pneumonia induced by multidrug-resistant P. aeruginosa by inhibiting the TLR4/NF-κB pathway." (PMID 40143103, 2025).
pneumonia (continued). "In summary, our results indicate that IA can bind to TLR4 protein and rely on it to inhibit excessive inflammatory expression in macrophages to alleviate pneumonia." (PMID 40736248, 2025). "Among these components, acanthoside D was reported to exhibit anti-inflammatory effects against TLR4-mediated pathway activation induced by LPS during a cell-based in vitro experiment as well as in vivo experiment using mice in pneumonia." (PMID 39860028, 2025). "In the in vivo murine pneumonia model, this method more accurately distinguished bacterial burdens at the site of infection (lung) and dissemination (spleen) between wild-type and Toll-like receptor 4 knockout mice." (PMID 41451991, 2025). "In vitro assays with HEK293-Blue reporter cells expressing murine and human Toll-like receptor 4 (TLR4) were used to assess LPS-associated toxicity, while in vivo reactogenicity and protective efficacy were evaluated in a murine acute pneumonia model." (PMID 41181323, 2025). "Anemoside B4 has been demonstrated to protect against Klebsiella pneumoniae-induced pneumonia via the TLR4/Mdy88 signaling pathway in mice." (PMID 38892715, 2024). "As a critical transmembrane recognition receptor of the innate immune system, TLR4 is involved in the occurrence of pneumonia and other inflammatory diseases, and NF-κB and MyD88 are its downstream molecules." (PMID 39472001, 2024). "We show that vascular-derived SPARLC1 exacerbates pneumonia by agonizing TLR4 and promoting the polarization of pro-inflammatory macrophages." (PMID 38762489, 2024). "Studies reported that LL‐37 exhibits modulation of immune and inflammatory factor secretion in inflammatory diseases, such as chronic obstructive pulmonary disease and pneumonia, and neutralizes LPS and thus inhibits TLR4 signaling pathway." (PMID 37773705, 2023). "Both reducted mortalities and K. pneumoniae-host disseminations were associated with TLR4 and TLR2 immune responses within the pneumonia mouse model." (PMID 36911530, 2023). "Previously, in vivo and in vitro studies of the K. pneumoniae meningitis revealed that the main memory impairment mechanism was due to IL-17 induction due to TLR4 signaling." (PMID 36015052, 2022). "Our findings revealed that LNT reduces the severity of pneumonia induced by IAV infection by modulating the TLR4/MyD88 signaling pathway, resulting in a more effective therapeutic impact." (PMID 35669119, 2022). "In contrast to the healthy control – COVID-19 pneumonia network, TLR4 was activated by downregulated let-7e-5p in the pneumonia–ARDS network." (PMID 34956213, 2021). "The comparison of the regulatory direction of TLR4 in COVID-19 pneumonia to COVID-19 ARDS showed inhibition of TLR4 by miR-146a-5p in pneumonia and upregulation in ARDS by downregulated let-7e-5p." (PMID 34956213, 2021). "Taken together, both the investigations suggested a protective role of XIST knockdown in LPS-induced inflammatory injury in WI-38 cells via sponging miRNAs, TLR4, and NF-κB pathways, thereby providing a novel target for the treatment of pneumonia." (PMID 33817304, 2021). "Taken together, anemoside B4 ameliorated FM1-induced pneumonia via the TLR4/MyD88 pathway with binding to TLR4." (PMID 32625244, 2020). "TLR4 is a leading actor in the resolution of the inflammatory response in pneumonia and TLRs are essential in the antiviral response triggering a strong inflammation involving interferon related genes, interleukins, chemokines as well as gal3 expression." (PMID 32973815, 2020). "Our findings demonstrated that anemoside B4 attenuates pneumonia via the TLR4/Myd88 signaling pathway, suggesting that anemoside B4 is a promising therapeutic candidate for bacterial-infected or viral-infected pneumonia." (PMID 32625244, 2020). "Previous study indicated that emodin can inhibit influenza viral-induced pneumonia via the TLR4 pathway." (PMID 32625244, 2020).
pneumonia (continued). "Here, we provide the first evidence for the regulatory impact of XIST through modulating miR‐370‐3p/TLR4 axis in pneumonia, thus providing new idea for pneumonia diagnosis and treatment." (PMID 31066476, 2019). "Next, Spearman's correlation analysis proved that XIST expression was positively while miR‐370‐3p expression was inversely correlated with TLR4 expression in acute‐stage pneumonia patients." (PMID 31066476, 2019). "We provide evidence that large volume resuscitation with stored blood, compared to fresh blood, in mice increases mortality from subsequent pneumonia, which occurs via mechanisms sensitive to hemopexin and TLR4 and HMGB1 inhibition." (PMID 29522519, 2018). "Thus, our results suggest that S. salivarius-derived IA alleviates pneumonia by modulating macrophage inflammation through the TLR4 signaling pathway, offering a promising therapeutic strategy for pneumonia caused by P. aeruginosa." (PMID 40736248, 2025). "Strong protective effect against LPS-induced pneumonia in mice by inhibiting TLR4/NF-JB/NLRP3." (PMID 39889188, 2025). "LPS was therefore used as a second stimulant in our neutrophil model as it mimics bacterial infection, allowing us to model a Gram-negative TLR4-mediated bacterial response which is a common cause of pneumonia." (PMID 38474145, 2024). "Similarly, Yang provided evidence that H19 silencing alleviates LPS-induced apoptosis and inflammation by regulating the miR-140-5p/TLR4 axis in cell models of pneumonia." (PMID 37841928, 2023). "Probiotics and prebiotics may treat allergic asthma inflammation and pneumonia induced by OVA-LPS by regulating TLR4/NF-kB signaling pathways." (PMID 37284648, 2023). "RNAseq identified hyaluronic acid as an upregulator of TLR4 in pneumonia and ARDS." (PMID 36776845, 2023). "Our results showed that compared with the Control group, the expressions of TLR4, MyD88, NF-κB, and ICAM-1 of the Model group were significantly higher (P < 0.01), indicating that the TLR4/MyD88/NF-κB signaling pathway was activated during the development of MDR PA-induced pneumonia in rats." (PMID 35071595, 2022). "To analyse the effects of S100A8/A9 and its counterreceptor TLR4 on platelets during acute pneumonia, we examined neutrophil recruitment in global S100A9−/− and conditional TLR4PF4Cre+ mice upon intratracheal infection with the clinically relevant pathogen K. pneumoniae." (PMID 36497202, 2022). "Collectively, our presented results suggest that SH may effectively treat P. aeruginosa-induced pneumonia in mice through the TLR4/NF-κB signaling pathway modulating immunity and affecting intestinal flora." (PMID 36530439, 2022). "miR-370-3p regulates LPS-induced acute pneumonia in WI-38 cells by targeting TLR4." (PMID 34301223, 2021). "Besides, the key signaling pathways including NF-κB and TLR4 were discovered to be highly induced in LPS-induced pneumonia in WI-38 cells, and this activation was suppressed by silencing CCL16, which was consistent with previous data." (PMID 33817304, 2021). "The aim of the study was to determine the molecular genetic prognostic criteria for the severity of pneumonia based on the analysis of the association of genetic polymorphisms of toll-like receptors (rs5743551 (TLR1), rs5743708 (TLR2), and rs4986790 (TLR4) loci) with the severity of NETosis." (PMID 34603755, 2021). "NEAT1 facilitated inflammatory injury and apoptosis in pneumonia through TLR4/NF-κB signaling." (PMID 34672863, 2021). "Therefore, anemoside B4 exhibited a significant therapeutic effect on pneumonia via the TLR4/MyD88 pathway." (PMID 32625244, 2020). "Moreover, the serum TLR4 expression in acute‐stage pneumonia patients was obviously higher than healthy control." (PMID 31066476, 2019). "Recently, several studies have highlighted the inflammatory role of TLR4 in pneumonia models." (PMID 31350813, 2019).